VIM (vimentin)
Diseases named in the same sentence as VIM in open-access papers (continued):
Sharing a sentence is not in itself a finding about the gene and the disease.
cervical carcinoma (continued). "In the co‐culture system of cervical cancer cells and SCs, signals from the cancer cells markedly enhanced the expression of GFAP, Vimentin and nestin in SCs." (PMID 37830980, 2023). "One study on cervical cancer cell lines reported that BAP1 knockdown induced increases in N-cadherin and vimentin and a decrease in E-cadherin (which are hallmarks of EMT) and increased cell migration." (PMID 37240204, 2023). "Snail, as a member of the zinc finger family of transcription factors, can bind to the E-cadherin gene to induce vimentin expression, and the high expression of Snail is closely related to the EMT process in cervical cancer." (PMID 35965516, 2022). "Compared to the control group, we found that epithelial marker E‐cadherin was up‐regulated in the si‐HSDL2 groups, while mesenchymal markers (Vimentin, Snail, Slug and MMP‐2) were considerably down‐regulated in all three cervical cancer cell lines." (PMID 33738911, 2021). "It suppressed cervical cancer cell migration by inhibiting the expression of positive regulators of epithelial-mesenchymal transition SNAI1 and VIM." (PMID 31527550, 2019). "We demonstrated that cervical cancer stem-like cells exhibit typical EMT features, including upregulated expression of EMT-related genes such as Vimentin, Twist 1, Twist 2, Snail 1 and Snail 2 and the potential to migrate through the basal membrane." (PMID 28912668, 2017). "The results from our univariate and multivariate analysis suggest that age and Vimentin expression exhibit a considerable impact on the OS and DFS of cervical cancer patients." (PMID 28912668, 2017). "We demonstrated that LSD1 binds to its upstream regulator (HPV16 E7), and its downstream target (Vimentin), to promote the EMT in cervical cancer." (PMID 27894088, 2017). "Our data built upon these studies, as we further elucidated that LSD1 was recruited to Vimentin promoter, demethylated H3K4me1 and H3K4me2, activated Vimentin transcription and thus served as a critical positive regulator of the EMT in cervical cancer." (PMID 27894088, 2017). "Additionally, the protein expression levels of Vimentin were closely correlated with the age of onset (P = 0.007), lymph node metastasis (P = 0.007), lymphatic invasion (P = 0.024), disease recurrence (P < 0.001), and the clinical prognosis of patients with cervical cancer (P < 0.001)." (PMID 28912668, 2017). "A chemoresistant cervical cancer cell line (SiHaCR) showed increased levels of HPV E6 and E7 transcripts and a mesenchymal phenotype, with upregulated snail/slug/twist/vimentin and downregulated E-cadherin." (PMID 29152102, 2017).
cervical carcinoma (continued). "The cervical cancer samples with episomal and integrated HPV16 genomes showed significantly increased expression of Vimentin by 3.66-fold (p<0.001) and 5.44-fold (p=0.014), respectively." (PMID 28402266, 2017). "We create poly(lactic-co-glycolic) acid NPs modified with MPG, polyethylene glycol (PEG), MPG/PEG, and Vimentin (VIM), and evaluate their cellular uptake in 2D (monolayer) cell culture of human cervical carcinoma (HeLa)." (PMID 27102372, 2016). "Consistent with the results of western blot, Ezrin KD significantly increased E-cadherin expression and decreased Vimentin, MMP-2, and β-catenin expression in HeLa and SiHa cells, suggesting that Ezrin KD inhibited EMT in cervical cancer cells in vitro." (PMID 26933912, 2016). "Transfection of normal human foreskin keratinocytes with HPV16 E7 induced the EMT program and cervical cancer cells transfected with HPV16 E6/E7 oncogenes experienced downregulation of E-cadherin and upregulation of vimentin." (PMID 26356073, 2015). "Knockdown of RIPK4 reduced cell migration and invasion via inhibition of Vimentin, MMP2 and Fibronectin expression in cervical cancer cells." (PMID 26148476, 2015). "As expected, our data suggest that HOTAIR knockdown was dysregulated the expression of EMT-related genes (E-cadherin, β-catenin, Vimentin, Snail and Twist), implying that these genes participate in HOTAIR-induced cervical cancer metastasis." (PMID 25405331, 2015). "Further studies revealed that suppression of RIPK4 expression significantly inhibited Vimentin, MMP2 and Fibronectin expression in two cervical cancer cell lines." (PMID 26148476, 2015). "The results suggest that Vimentin and E-cadherin are involved in the regulatory role of NEDD9 on cell migration and invasion in cervical cancer cells." (PMID 24058594, 2013). "Cervical cancer cells conditioned media from HeLa and SiHa cells do not induce vimentin expression significantly; however, the integrated density of expression is very strong in the cytoplasmic region of stimulated MSCs." (PMID 38606999, 2024). "To determine whether cervical cancer cells conditioned media (SiHa and HeLa) can promote differentiation towards an MSC-CAF phenotype we evaluated vimentin, S100A4, αSMA, FAP, and MMP9 expression by immunofluorescence." (PMID 38606999, 2024). "In addition, we investigated the protein levels of vimentin, S100A4, αSMA, FAP, MMP9, and Ki67 in different stages of cervical cancer." (PMID 38606999, 2024). "Thus, our results indicated that cervical cancer cells had a strong glial cell‐activating property that induced GFAP and Vimentin expression in SCs partially via the PACAP paracrine signalling." (PMID 37830980, 2023). "In cervical cancer, compared to SOX2-negative cells, tumor cells that endogenously express SOX2 exhibit an enhanced stemness phenotype along with decreased expression of E-cadherin and Vimentin and a high degree of invasive metastatic capacity." (PMID 37213675, 2023). "Immunohistochemical analysis showed that during the cervical cancer stage, HIV-positive patients exhibited significantly decreased levels of E-cadherin and cytokeratin, and increased levels of vimentin in cervical lesion tissues as compared to HIV-negative patients (all P < 0.05)." (PMID 37981694, 2023). "Immunohistochemical staining showed that E‐cadherin expression was more in the Juglone‐treated tumor than in the DMSO treated tumor, and Vimentin expression was less than in the DMSO‐treated tumor, indicating that downregulation of Pin1 expression inhibits EMT in cervical cancer in vitro." (PMID 36684109, 2023). "Vimentin, as an important cytokine that stimulates tumor progression, is mainly distributed in mesenchymal tissues and is increased during the EMT process and cervical cancer progression." (PMID 35965516, 2022).
cervical carcinoma (continued). "In this paper, the cholesterol level and 3-hydroxy-3-methylglutaryl coenzyme a reductase (HMGCR) phosphorylation were investigated in vimentin knockout (KO) and human cervical carcinoma cells (HeLa) cell with or without AIV infection." (PMID 36016436, 2022). "In vitro, The proliferation, migration and invasion of cervical cancer cells were significantly inhibited after knocking down of FABP4, which was accompanied by elevated expression of E-cadherin and downregulated expression of N-cadherin, Vimentin and p-AKT." (PMID 34702269, 2021). "IL‐6 was used to activate STAT3 signaling pathway in HeLa and SiHa cells, and the expression of N‐cadherin, E‐cadherin, vimentin, MMP‐3, and MMP‐13 were examined to confirm the activation of the STAT3 signaling pathway to promote the invasion potential of cervical cancer cells." (PMID 33040485, 2020). "HeLa and SiHa cells were treated with RES and S3I201 or AG490, and the expression levels of N‐cadherin, E‐cadherin, vimentin, MMP‐3, and MMP‐13 were examined to confirm that the role of STAT3 phosphorylation was inhibited by RES on the invasion potential of cervical cancer cells." (PMID 33040485, 2020). "A finding similar to ours was that HOXC6 gene silencing delays EMT (reflected by decreased N-cadherin and Vimentin expression and increased E-cadherin expression) through the inhibition of the activation of TGF-β/Smad signaling pathway in cervical carcinoma cells." (PMID 32171324, 2020). "Furthermore, a multivariate analysis also reveals that Vimentin expression is an independent prognostic factor for the OS and DFS of cervical cancer patients." (PMID 28912668, 2017). "Both E-Cadherin and Vimentin expression failed to differ significantly between the cervical cancer cases with episomal and integrated HPV16 genomes." (PMID 28402266, 2017). "Vimentin, which functions as a key intermediate filament protein in mesenchymal cells, is involved in EMT and plays a critical role in the growth, invasion and metastasis of human cancer cells, including cervical cancer." (PMID 28912668, 2017). "However, HPV E6/E7-transfected cervical cells showed upregulated vimentin expression and downregulated E-cadherin protein expression, suggesting a possible role for HPV in the development of EMT in cervical cancer." (PMID 29152102, 2017). "Vimentin, on the other hand, showed a significantly increased expression among the cervical cancer cases (3.83-fold; p=0.001), as compared to the HPV negative control samples." (PMID 28402266, 2017). "Immunohistologically, typical cases of endometrial cancer are positive for ER and vimentin and negative for CEA, whereas cervical cancer shows the opposite pattern of negative for ER and vimentin and positive for CEA." (PMID 21886452, 2011). "In this study, NR5A2 was identified to express differentially between metastatic and non-metastatic tissues of cervical cancers, and may promote the tumorigenesis and metastasis by regulating VIM." (PMID 33842467, 2021). "Furthermore, Western blot analysis was used to detect the expression of N‐cadherin, vimentin, MMP‐2 and MMP‐9 in cervical cancer cells, the results of which showed an up‐regulation in these proteins upon E2F4 silencing or C16orf74 overexpression in the presence of HAND2‐AS1 overexpression (P < .05)." (PMID 32314545, 2020). "The protein levels of p‐STAT3 (Tyr705), N‐cadherin, E‐cadherin, vimentin, MMP‐13, and MMP‐3 in the tumor tissues grown from HeLa cells were determined through IHC and Western blot to examine the effects of RES on STAT3 phosphorylation, EMT, and cervical cancer cell invasion." (PMID 33040485, 2020).
cervical carcinoma (continued). "Previously, it was found that stimulation of cervical carcinoma A431 cells by recombinant MMP-9 led to an acquisition of spindle-like phenotype by the cells; furthermore, knockdown of MMP-9 by siRNA significantly reduced expression of mesenchymal markers vimentin and fibronectin in these cells." (PMID 33327637, 2020). "Although our western blot data demonstrate that N. brasiliensis L3 antigen significantly reduces the expression of vimentin in cervical cancer cells, it is not known how antigen exposure alters cell-surface vimentin expression or the uptake of HPV pseudovirions." (PMID 30069018, 2018). "In cervical cancer, human papilloma virus (HPV) oncogene E6 has been shown to induce a mesenchymal phenotype in a chemoresistant cervical cancer cell line (SiHaCR), with elevated levels of survivin, snail, slug, twist and vimentin and reduced levels of E-cadherin." (PMID 29152102, 2017). "Nevertheless, it is still unknown whether or not the expression of Vimentin is correlated with the clinicopathologic features of cervical cancers." (PMID 28912668, 2017). "Also, si-circCLK3 increased E-cadherin expression and down-regulated Vimentin and N-cadherin expression, while overexpression of circCLK3 decreased E-cadherin expression and up-regulated Vimentin and N-cadherin expression, indicating that circCLK3 promotes EMT of cervical cancer." (PMID 31831728, 2019). "Crinamine induces cell apoptosis without promoting DNA double strand breaks and suppresses cervical cancer cell migration by downregulating SNAI1 and VIM expression, positive regulators of epithelial-mesenchymal transition." (PMID 38751791, 2024).
lung adenocarcinoma (111 papers, 2006 to 2026). A carcinoma that arises from the lung and is characterized by the presence of malignant glandular epithelial cells. "We observed that exosomes isolated from patients with EGFR-mutated lung adenocarcinoma promoted extracellular matrix degradation and a significantly increased expression of vimentin in recipient A549 cells." (PMID 35954442, 2022). "A correlation between high vimentin expression and lung adenocarcinoma tumors bearing KRAS-G12C mutation was also observed." (PMID 34198671, 2021). "vimentin is an intracellular protein found upregulated in lung adenocarcinoma and large cell lung cancer and linked to cancer invasion and metastasis." (PMID 32842557, 2020). "The process allowed the successful selection of four aptamers (LC-183, LC17, LC-18, LC-110) and the identification of eight potential lung adenocarcinoma cell protein biomarkers associated, including cathepsin D, vimentin, annexins, histone2B." (PMID 32842557, 2020). "Loss of SARI (suppressor of AP-1, also called BATF2) expression initiates EMT, causing repression of E-cadherin and upregulation of vimentin in lung adenocarcinoma cell lines and in human lung adenocarcinomas." (PMID 27018053, 2016). "In other studies, in human lung adenocarcinoma, PC downregulation appeared to be intimately associated with upregulation of vimentin and E-cadherin, both involved in mesenchymal transition." (PMID 23768159, 2013). "In patients with stage IV EGFR-mutant lung adenocarcinoma, high E-cadherin expression in the lung tumor might be associated with worse OS, and vimentin expression in the lung tumor was positively related to the risk of brain metastasis." (PMID 37340370, 2023). "Furthermore, increased ER stress, as demonstrated by increased Bip, Chop, PDI, Ero1α and IRE1, and EMT, as demonstrated by increased Vimentin and Snail, is a hallmark of primary lung adenocarcinoma samples from patients." (PMID 28186986, 2017). "We found that the up-regulation of methionine synthase reductase (MTRR) by regulating the phosphorylation of vimentin Ser56 in SCAPEP is a key mechanism driving the aggressiveness of SCAPEP -high lung adenocarcinoma." (PMID 42091858, 2026). "It has been reported in lung adenocarcinoma that spheroids show overexpression of mesenchymal markers like vimentin and downregulation of epithelial markers like E-cadherin." (PMID 40394426, 2025). "Knockdown of PKD2 in lung adenocarcinoma cell lines significantly reduced the expression of mesenchymal markers (N-cadherin, vimentin) and transcription factors (Twist, Snail) that promote EMT; it also inhibited cell migration and invasion." (PMID 39408603, 2024). "Western blot analysis showed that the expression of E-cadherin increased in lung adenocarcinoma cells after radiation, while the expression of Vimentin decreased significantly, suggesting that the process of EMT was induced by radiation." (PMID 38341398, 2024). "The FGFR1/JNK/Vimentin/Snail signalling cascade emerges as a pivotal pathway governing EMT in lung adenocarcinoma through TMEM176B overexpression, and this suggests that TMEM176B is a potential therapeutic target for lung adenocarcinoma." (PMID 39001509, 2024). "To study the molecular response to hypoxia on motility we measured the mRNA levels of main EMT markers, namely vimentin, N-cadherin, and E-cadherin in our panel of lung adenocarcinoma cell lines." (PMID 39227650, 2024). "Proteomic analysis on lung adenocarcinoma cells overexpressing KPNA2 revealed that an enhanced interaction between vimentin and KPNA2 leads to the recruitment of phosphorylated ERK in the cytoplasm." (PMID 37792911, 2023). "Here, a novel modification of vimentin, acetylated at Lys104 (vimentin‐K104Ac) is identified, which is stable in lung adenocarcinoma (LUAD) cells." (PMID 37424170, 2023). "Our study revealed the possible role of E-cadherin and vimentin expression in EGFR-mutant lung adenocarcinoma." (PMID 37340370, 2023).